FOXA2 (forkhead box A2)
Diseases named in the same sentence as FOXA2 in open-access papers (continued):
Sharing a sentence is not in itself a finding about the gene and the disease.
cancer (continued). "However, genes associated with cell differentiation (EPCAM, CK8, CK18, and FOXA2), EMT (SNAI1, FOSL1, and ID1), and cancer stem cells (CD44, CD133, ETV1, MALAT1, NEAT1, and NESTIN) displayed a more varied response compared to 2D cells." (PMID 33356003, 2021). "A previous study has demonstrated that FOXA2 is hypermethylated in various cancer cell lines." (PMID 33927349, 2021). "Notably, previous studies reported that the dysfunction of FOXA2 is related to the prognosis of several cancers." (PMID 31689237, 2019). "Moreover, a recent study has demonstrated that FOXA1 and/or FOXA2, together with other master transcription factors, are essential for the maintenance of cancer cell states through the recruitment of the mediator–cohesin complex." (PMID 30360388, 2018). "Foxa2 has been proposed as a mesenchymal-to-epithelial transition (MET) driver in murine loss-of-function studies and in various human cancers." (PMID 29915126, 2018). "To investigate whether FOXA2-DS-S tapRNA has a functional effect in cancer, we knocked it down in Huh7 and A549 cells." (PMID 29540241, 2018). "Taken together, FOXA2 is a stemness regulator in normal stem cells and cancer stem cells." (PMID 29187221, 2017). "In the current study, we found that the size and number of spheres derived from 3AO and SKOV3 cells, and the percentage of cells bearing cancer stem cell phenotype markers in spheres, were all depressed after FOXA2 was knocked down, suggesting that FOXA2 modulates self-renewal of OCSCs." (PMID 29187221, 2017). "Four transcription factors, EGR1, HNF4A, MITF and FOXA2, appeared to form a hub of upstream regulators in all five gene-sets (p < 0.001) and could explain the apparent overlap in disease outcomes (ie. cancer)." (PMID 28531178, 2017). "Interestingly, cancer cell proliferation was impaired in vitro upon depletion of either FoxA1 or FoxA2 in MCF7 and MDA231 cells, respectively." (PMID 27045898, 2016). "Furthermore, it has been reported that some of these genes (e.g. Foxa2 and Msx2) are able to change gene expression patterns in human cancer." (PMID 27711132, 2016). "Little is known about the ratio of FOXA1 to FOXA2 in cancer." (PMID 26658322, 2015). "To identify FoxA2 occupied sites at active and inactive genes relevant to endoderm-derived tissue in the adult liver, we designed a high-density tiling microarray covering 210 genes related to endoderm, liver, pancreas, lung, gut, signaling, and cancer." (PMID 21935353, 2011). "However, the role of the FOXA1 to FOXA2 transition in regulating cancer lineage plasticity remains unclear." (PMID 38851846, 2024). "Similarly, FOXA2 also has oncogenic potential and its role has been elucidated in many cancers." (PMID 33344262, 2020). "Also, curcumin treatment increased Bax expression in NCI-H292 cells; therefore, cancer cell growth inhibition by curcumin may be due to FOXA2-induced Bax upregulation." (PMID 29456509, 2018). "In addition to the prognostic value, suppression of the LINC00261/FOXA2 locus may be a targetable node in the process of pathological EMT during cancer progression." (PMID 30597925, 2018). "Recent research has shown that curcumin targets cancer stem cell phenotypes in ex vivo models of colorectal liver metastases, through increased apoptosis and decreased levels of cancer stem cell markers (Nanog, Oct-3/4, HNF/FoxA2, VEGFR, ALDH1)." (PMID 39859345, 2025). "These experiments indicated that FOXA2 was an upstream regulator of RND1, thus affecting the DDP resistance of cancer cells." (PMID 39129202, 2024).
cancer (continued). "To investigate the role of FOXA2 in RCC development, we knocked down FOXA2 in two RCC cancer lines, A498 and 769P, by two independent interference RNAs, which reduced FOXA2 expression to less than 80% of the scrambled negative controls (NC)." (PMID 38072043, 2023). "Third, reexpression of WT FOXA2 in the well-differentiated ISK EC cell line led to pronounced suppression of growth– and other cancer–related phenotypes." (PMID 35703180, 2022). "By using different model systems including combined Phf8 knockout and the TRAMP mouse model, NEPC cell lines, NEPC PDX and patients' cancer tissues, we established the PHF8/FOXA2 axis and illustrated its role in NEPC development." (PMID 33009820, 2021). "For example, FOXA1 and FOXA2, both of which play an important role in α-cell glucagon biosynthesis and secretion, are O-GlcNAc modified by OGT in cancer cells, and this modification is important for the stability of the protein." (PMID 33460647, 2021). "This positive transcriptional correlation was evident even in other cancers, and in normal tissues, both LINC00261 and FOXA2 were highly co‐expressed in endoderm‐derived organs." (PMID 33793068, 2021). "Foxa2 is an EMT suppressor but also an epithelial gatekeeper; thus, maintaining FOXA2 expression during cancer initiation and progression will prevent a complete EMT–MET cycle and eventually cancer dissemination." (PMID 34168324, 2021). "FoxA1 and FoxA2 were mainly localized in the nuclei of normal bile duct (NBD) cells and some of the cancer cells." (PMID 32151057, 2020). "We propose that CX3CL1, E-cadherin, N-cadherin, and FOXA2 show a lot of potential as downstream target genes of hsa-miR-590-3p signifying hsa-miR-590-3p's indirect effect on EMT and in turn cancer progression." (PMID 31781476, 2019). "Foxa2 has been reported to suppress EMT and inhibit motility and invasiveness of cancer cell lines derived from tumors of endodermal origin." (PMID 26395490, 2015). "Among the candidates expressed in cancer cells, differential expression between never-met versus met-associated SCLC primary tumors was greatest for FOXA2." (PMID 40419484, 2025). "Moreover, we reveal that FOXA2 collaborates with JUN at chromatin and promotes transcriptional reprogramming of AP-1 in lineage-plastic cancer cells, thereby facilitating cell state transitions to multiple lineages." (PMID 38851846, 2024). "The results included well-known cancer genes such as MYC, FOXA2 and FADD, and the unknown SLITRK3 gene." (PMID 35006496, 2021). "Notably, at least two of the FOXA2 transcriptional targets identified by our analysis (ANK2 and RAB3C) are known to promote cancer progression and metastasis." (PMID 33793068, 2021). "A comparison of the expression levels of the 12 TFs in normal mucosa and MSS and MSI cancers revealed that FOXA2 was significantly (P<0.01) deregulated in MSS but not MSI cancers explaining why it was found to be differentially expressed between MSS and MSI." (PMID 19156145, 2009). "Therefore, MYB, HDAC2, and FOXA2 are master regulators in controlling the Boolean GRN model toward an enterocyte state and could be effective targets for cancer treatment." (PMID 39661721, 2025). "Foxa2 mice exhibited normal uterine weights, and while Pten uteri had increased weights, this was due to significantly longer uterine horns and not invasive cancers." (PMID 35703180, 2022). "Hence, our data suggest that a focus on FOXA2 in HCC may help address the problem of JQ1’s and potentially other BET inhibitors’ detrimental effects in anti-cancer therapy." (PMID 35546353, 2022).
infection (15 papers, 2010 to 2026). The state of being infected such as from the introduction of a foreign agent such as serum, vaccine, antigenic substance or organism. "The induction of mucus secretion associated to mild infection by Pneumocystis has been described as part of a STAT6/FoxA2 pathway immune response, leading to the increment of the levels of the two most relevant mucins of the airways: Muc5ac and Muc5b." (PMID 37108906, 2023). "Host gene variants involved in trafficking (FYCO1 and RAB7A) and immune signaling (FOXA2, SFTPD, STAT3, and TET2) were associated with differential infection profiles." (PMID 41683583, 2026). "FOXA2 expression in BMSCs was inhibited by infection with FOXA2 shRNA lentivirus (sh-FOXA2) (P < 0.01), followed by the combined treatment with sh-SNHG14." (PMID 36644009, 2023). "The epithelial gene FOXA2 showed only a minor decrease at 2 dpi, compatible with an overall preservation of the epithelial layer upon infection." (PMID 34272374, 2021). "FOXA2 expression was determined by quantitative PCR (qPCR), immunofluorescence (IF), and western blotting 5 days after infection and screening." (PMID 30082727, 2018). "Foxa2 is involved in the transcriptional regulation of DEFB1, and downregulation of DEFB1 due to suppression of Foxa2 expression is likely to contribute to increased infection risk in the Th2-dominated airway inflammation." (PMID 31881038, 2019). "We found three genes that were commonly activated with infection with SCV2 at both 12 and 24 hpi (DUSP1, HES1, KLF2) and some non-congruent genes at 12 hpi (CCL5, ZBP1, NRXN2, STAB1, SLC25A47, CXCL11) and 24 hpi (FOXA2, RHOB)." (PMID 37504520, 2023). "At 12 days after infection with GLI-IRES-EGFP, 63.27% ± 4.85% SEM cells were FOXA2+." (PMID 20799336, 2010). "Furthermore, our transcriptional profiling predicted a dysregulation of the transcription factor Foxa2 in the absence of IL-13 after infection." (PMID 34127548, 2021). "Also the expression of transcription factors was significantly modified by HHV-6A/6B infection, with an early increase of ATF3, JUN and FOXA2 by both species, whereas HHV-6A specifically induced a 15-fold decrease of POU2AF1, and HHV-6B an increase of FOXO1 and a decrease of ESR1." (PMID 29163428, 2017). "Transcripts for canonical β-cell markers including PDX1, FOXA2, G6PC2, and PAX6 were present at low levels and also decreased following infection but were not amongst the top 1000 differentially expressed transcripts." (PMID 32093375, 2020). "Following infection, ENVY cells were harvested and then cocultured with a non-GFP hESC line, HES-3, for 12 days after which FOXA2+/GFP− cells were identified." (PMID 20799336, 2010).
adenocarcinoma (12 papers, 2007 to 2025). A common cancer characterized by the presence of malignant glandular cells. "AdSCC in the KrasLSL-G12D/+; Nkx2-1F/F; Foxa1F/F mouse exhibited the opposite pattern, that is, FoxA1 loss in both components and FoxA2 expression only in the adenocarcinoma component." (PMID 30475207, 2018). "As expected, AdSCCs in KrasLSL-G12D/+; Nkx2-1F/F; Foxa1F/F; Foxa2F/F mice always expressed either FoxA1 or FoxA2 in the adenocarcinoma component and stochastic loss of the other paralogue in the squamous component." (PMID 30475207, 2018). "In alignment, FOXA2 expression was elevated in NEPC compared with lineage-plastic neuroendocrine-like or adenocarcinoma cell lines." (PMID 39470735, 2024). "Interestingly, FOXA2 transcription factor is known to be upregulated in KIF5B-RET fusion adenocarcinomas through RET downstream signaling pathways such as ERK and AKT." (PMID 38132167, 2023). "Finally, the IHC scores of the PHF8 and FOXA2 staining in 59 adenocarcinoma, 13 CRPC‐Adeno, and 10 NEPC or NED specimens indicate that expression of PHF8 and FOXA2 in NEPC tissues is much higher than in adenocarcinoma (Adeno) and CRPC‐Adeno tissues." (PMID 33009820, 2021). "FoxA1 and FoxA2 were expressed in the adenocarcinoma component of all cases." (PMID 30475207, 2018). "This phenomenon was rarely observed in tumors from other control groups, which predominantly produced intracellular mucin, suggesting that FoxA1 and FoxA2 likely have some specific functions in the regulation of the differentiation state of NKX2-1-negative adenocarcinoma." (PMID 30475207, 2018). "Furthermore, results from research using the transgenic adenocarcinoma of the mouse prostate (TRAMP) mouse model indicate that FOXA2 functions together with HIF1α to drive a transcriptional program essential for NEPC development, thus establishing FOXA2 as a driving factor for NEPC." (PMID 33009820, 2021). "Further examination revealed that ENZ treatment induced the expression of NR1D1/REV-ERBα and LP drivers, such as BRN2, ASCL1, FOXA2, and ONECUT2, in a dose and time-dependent manner in adenocarcinoma cells, with REV-ERBα being the fastest and strongest induced among them." (PMID 41231955, 2025). "In KrasLSL-G12D/+; Nkx2-1F/F; Foxa2F/F mice, we found that FoxA2 was absent in both components, whereas FoxA1 was expressed in the adenocarcinoma components but absent in the SCC." (PMID 30475207, 2018).
metabolic disease (4 papers, 2020 to 2024). A congenital disorder (due to inherited enzyme abnormality) or acquired (due to failure of a metabolically important organ) disorder resulting from an abnormal metabolic process. "The molecular mechanism linking lipid-based abnormalities to metabolic disorders has been shown to be associated with insulin-mediated FOXA2 repression in obese and high-fat diet states, leading to elevated triglycerides and reduced plasma high-density lipoprotein (HDL) levels." (PMID 35973994, 2022). "In obese and high-fat diet states, insulin-mediated FOXA2 repression has been shown to be the molecular mechanism linking lipid-based abnormalities to metabolic disorders." (PMID 38627644, 2024). "Third, metabolic diseases can be treated by directly knocking out FOXA1 and FOXA2, but this approach also causes the original physiological effects to disappear, leading to side effects such as incomplete organ development and differentiation." (PMID 38605023, 2024). "We should selectively target the upstream regulatory factors of FOXA1 and FOXA2 in metabolic diseases or downstream regulatory factors to achieve therapeutic effects." (PMID 38605023, 2024). "Gene ontology analysis suggested a biological role of FoxA2 in inflammatory response, metabolic disease, organismal injury and abnormalities, lipid metabolism, and molecular transport." (PMID 32143325, 2020).
inflammation (3 papers, 2018 to 2022). Aberrant reaction of the microcirculation characterized by movement of fluid and leukocytes from the blood into extravascular tissues. "The deletion of FOXA2 has been found to cause goblet cell metaplasia and Th2-mediated lung inflammation in respiratory epithelia." (PMID 36505412, 2022). "Of interest, loss of Foxa2 expression in lung epithelium in a mouse model not only induced goblet cell metaplasia, but also spontaneous pulmonary eosinophilic inflammation, recruitment of mDCs and type-2 T cells and increased levels of various chemokines, including CCL1742." (PMID 30185803, 2018).
lung (3 papers, 2015 to 2025). "Consequently, we selected eight statistically significant TACTs—EPCAM, KRT19, ERBB2, MKI67, MCAM, FOXA2, SNAI2, and NPTN—which we designated as colorectal TACTs (C-TACTs)." (PMID 40003943, 2025). "Previous reports have shown that gastric differentiation program was triggered in murine lung ADC following NKX2‐1 deletion, which involved the interaction of NKX2‐1 and FOXA1/FOXA2 to re‐program FOXA1/FOXA2 binding sites and preferential activation of certain target genes." (PMID 33439550, 2021).
neurodegenerative disease (2 papers, 2024). A disorder of the central nervous system characterized by gradual and progressive loss of neural tissue and neurologic function. "It has been reported to differentiate neural stem cells into dopaminergic neurons via upregulating the TET1 and FoxA2 expression and their binding, indicating potential application as neural stem cell replacement therapy for neurodegenerative diseases." (PMID 38505421, 2024).
musculoskeletal diseases (1 paper, 2020). "It is conceivable that certain myositis disorders or other forms of painful musculoskeletal diseases could benefit from approaches that increase FoxA2 activity in skeletal muscles." (PMID 32143325, 2020). "Therefore, it is conceivable that certain myositis disorders or other forms of painful musculoskeletal diseases may benefit from approaches that increase FoxA2 activity in skeletal muscle." (PMID 32143325, 2020).
respiratory diseases (1 paper, 2023). "In fact, several genes are involved in respiratory diseases (BMALl1, FOXa2, CKIε, PER3, TIM, RORα, Clock, PER2-3, BHLHE40-41, REV-ERBα, and CRY1-2)." (PMID 38067152, 2023).
FOXA2 also shares sentences with these, for which no sentence is quoted: non-small cell lung carcinoma (4 papers); mucinous adenocarcinoma (3); Cirrhosis (2); developmental delay (2); genitourinary cancers (2); Hypertension (2); hypothyroidism (2); intrahepatic cholestasis (2); MODY (2); allergic disease (1); anal atresia (1); ankylosing spondylitis (1); autism (1); carcinosarcoma (1); cardiovascular disease (1); cervical squamous cell carcinoma (1); Cholestatic liver disease (1); chordoma (1); colorectal tumors (1); congenital heart disease (1); congenital hypopituitarism (1); coronary atherosclerosis (1); cystic fibrosis (1); dysplasia (1); endometrioid endometrial carcinomas (1); familial restrictive cardiomyopathy-6 (1); Fanconi anemia (1); gastritis (1); gastroesophageal junction adenocarcinoma (1); gestational diabetes mellitus (1).
A further 27 diseases each share a sentence with FOXA2 in 1 paper.